UBE2D1 (ubiquitin conjugating enzyme E2 D1)
Description:
Accepts ubiquitin from the E1 complex and catalyzes its covalent attachment to other proteins. In vitro catalyzes 'Lys-48'-linked polyubiquitination. Mediates the selective degradation of short-lived and abnormal proteins. Mediates ubiquitination of PEX5 and auto-ubiquitination of STUB1, TRAF6 and TRIM63/MURF1. Ubiquitinates STUB1-associated HSP90AB1 in vitro. Lacks inherent specificity for any particular lysine residue of ubiquitin. Essential for viral activation of IRF3. Mediates polyubiquitination of CYP3A4.
Synonyms: SFT; UBCH5; UBCH5A; UBC4/5; E2(17)KB1
Tractability: Small molecule: a structure with a bound ligand is known. PROTAC: UniProt records ubiquitination sites on it; ubiquitination databases record sites on it; its protein half-life has been measured.
Target class: Enzyme; Transferase
Gene: Protein-coding gene on chromosome 10 (58,334,975 to 58,370,751, forward strand). Ensembl gene ENSG00000072401.
Subcellular location: Cytoplasm
Subcellular location (Human Protein Atlas): Cytosol; Plasma membrane
Pathways (Reactome):
Cell Cycle: APC-Cdc20 mediated degradation of Nek2A; APC/C:Cdc20 mediated degradation of Cyclin B; APC/C:Cdc20 mediated degradation of Securin; APC/C:Cdc20 mediated degradation of mitotic proteins; APC/C:Cdh1 mediated degradation of Cdc20 and other APC/C:Cdh1 targeted proteins in late mitosis/early G1; Autodegradation of Cdh1 by Cdh1:APC/C; Cdc20:Phospho-APC/C mediated degradation of Cyclin A; Conversion from APC/C:Cdc20 to APC/C:Cdh1 in late anaphase; Inactivation of APC/C via direct inhibition of the APC/C complex; Phosphorylation of the APC/C; Regulation of APC/C activators between G1/S and early anaphase; Separation of Sister Chromatids
Immune System: Antigen processing: Ubiquitination & Proteasome degradation; CLEC7A (Dectin-1) signaling; Downstream TCR signaling; FCERI mediated NF-kB activation; IKK complex recruitment mediated by RIP1; Inactivation of CSF3 (G-CSF) signaling; Negative regulators of DDX58/IFIH1 signaling; TICAM1, RIP1-mediated IKK complex recruitment
Metabolism of proteins: E3 ubiquitin ligases ubiquitinate target proteins; Neddylation; Ovarian tumor domain proteases; Ribosome Quality Control (RQC) complex extracts and degrades nascent peptide; Synthesis of active ubiquitin: roles of E1 and E2 enzymes; ZNF598 and the Ribosome-associated Quality Trigger (RQT) complex dissociate a ribosome stalled on a no-go mRNA
Signal Transduction: Downregulation of SMAD2/3:SMAD4 transcriptional activity; Regulation of TNFR1 signaling; Signaling by BMP
Cellular responses to stimuli: Oxygen-dependent proline hydroxylation of Hypoxia-inducible Factor Alpha; Senescence-Associated Secretory Phenotype (SASP)
DNA Replication: Assembly of the pre-replicative complex; CDK-mediated phosphorylation and removal of Cdc6
Circadian clock: Degradation of CRY and PER proteins
Disease: Aberrant regulation of mitotic exit in cancer due to RB1 defects
Gene expression (Transcription): Transcriptional Regulation by VENTX
Protein localization: Peroxisomal protein import
Gene Ontology:
Molecular function: protein binding; ubiquitin conjugating enzyme activity; ubiquitin protein ligase activity; ubiquitin-protein transferase activity
Biological process: negative regulation of TORC1 signaling; positive regulation of protein ubiquitination; proteasome-mediated ubiquitin-dependent protein catabolic process; protein K48-linked ubiquitination; protein polyubiquitination; ubiquitin-dependent protein catabolic process; negative regulation of BMP signaling pathway; negative regulation of transcription by RNA polymerase II; protein ubiquitination
Cellular component: cytoplasm; cytosol; protein-containing complex; nucleoplasm
Genetic constraint (gnomAD): Loss-of-function variants: 3 observed, 10.53 expected, observed/expected ratio (o/e) 0.28, 90% interval 0.13 to 0.74. The upper end of that interval is the gene's LOEUF score, 0.74, which puts it in group 3 of 6, group 1 being the genes least tolerant of losing a copy. Missense variants: 48 observed, 95.48 expected, observed/expected ratio (o/e) 0.5, 90% interval 0.4 to 0.64. Synonymous variants: 35 observed, 31.69 expected, observed/expected ratio (o/e) 1.1, 90% interval 0.84 to 1.46.
Homologues: Orthologues: chimpanzee UBE2D1 (100% identical), dog UBE2D1 (100% identical), mouse Ube2d1 (100% identical), pig UBE2D1 (100% identical), macaque UBE2D1 (96% identical), guinea pig UBE2D1 (95% identical), rat Ube2d1 (95% identical), tropical clawed frog ube2d1 (95% identical), zebrafish ube2d1b (95% identical), zebrafish ube2d1a (92% identical), Caenorhabditis elegans let-70 (89% identical), Drosophila melanogaster eff (89% identical). Paralogues in human: UBE2D4 (90% identical), UBE2D2 (87% identical), UBE2D3 (86% identical), UBE2E1 (61% identical), UBE2E2 (61% identical), UBE2E3 (61% identical), UBE2L3 (39% identical), UBE2L5 (39% identical), UBE2L6 (39% identical), UBE2Q1 (31% identical), UBE2Q2 (30% identical), UBE2QL1 (27% identical).